CD99P1 (CD99 molecule pseudogene 1)
Synonyms: formerly MIC2R; NCRNA00103; CXYorf12; CD99L1
Gene: Transcribed unprocessed pseudogene on chromosome X (2,609,415 to 2,623,453, forward strand). Ensembl gene ENSG00000223773.
Diseases named in the same sentence as CD99P1 in open-access papers:
CD99P1 is named in the same sentence as 4 diseases in open-access papers, as found by Europe PMC text mining. Sharing a sentence is not in itself a finding about the gene and the disease.
CD99P1 shares sentences with these, for which no sentence is quoted: asthma (1 paper); diabetes (1); glioma (1); nicotine addiction (1).